VCAM1 (vascular cell adhesion molecule 1)
Diseases named in the same sentence as VCAM1 in open-access papers (continued):
Sharing a sentence is not in itself a finding about the gene and the disease.
atherosclerosis (continued). "First, reduced surface levels of several adhesion molecules, with decreased monocyte (subset) adhesion to vascular cell adhesion molecule-1, after LSFD is expected to decrease monocyte infiltration into arterial walls and may therefore decelerate atherosclerosis progression." (PMID 37325398, 2023). "VCAM1 has been reported to be blocked through various approaches, such as neutralizing antibody, genetical modification, or chemical compounds (e.g., AGI-1067), to improve atherosclerosis, rheumatoid arthritis (RA), nonalcoholic steatohepatitis (NASH), and so on." (PMID 37841916, 2023). "TMAO contributes to the early pathological process of atherosclerosis through accelerating endothelial activation and dysfunction, including reduced endothelial self-renewal and increased monocyte adhesion through activation of PKC/NF-κB/vascular cell adhesion molecule-1 (VCAM-1)." (PMID 37833946, 2023). "Moreover, thymol has been revealed to prevent the development of atherosclerosis by suppressing inflammatory mediators: IL-1β, IL-6, TNF-α, and TNF-β and adhesion molecules: vascular cell adhesion molecule-1 (VCAM-1), MCP-1, and matrix metalloproteinase 9 (MMP-9) in hyperlipidemic rabbits." (PMID 36982410, 2023). "Importantly, the genetic variation in the Vcam1+ SMCs and Col2a1+ SMCs contributed to CAD heritability beyond other cell states, suggesting that these cell states are particularly important in understanding the pathobiology of atherosclerosis." (PMID 37060905, 2023). "This decrease of de novo atherosclerosis in the absence of TRAF1 is accompanied by a lower content of macrophages and lipids in TRAF1-deficient plaques, an effect likely caused by reduced VCAM-1 and ICAM-1 expression on EC and reduced β1-integrin expression on macrophages." (PMID 35252400, 2022). "Finally, previous studies found that statins inhibit the expression of adhesion molecules such as vascular cell adhesion molecule-1 (VCAM-1) and intercellular cell adhesion molecule-1 (ICAM-1) in vascular endothelial cells, preventing atherosclerosis progression." (PMID 35328466, 2022). "We determined the expression of Cxcl12, Vcam1, Scf (Kitl) and Angpt1, thus sampling the canonical factors supplied by various niche cells to promote HSPC retention and quiescence in steady state that decline after acute MI37 in mice with hypertension or atherosclerosis." (PMID 35747128, 2022). "Similarly, aloperine treatment also reduced oxidized low-density lipoprotein, a marker of endothelial inflammation, and reduced MCP-1, VCAM-1, IL-6, and E-selection by reducing Kruppel-like factor 2 (KLF2) expression, suggesting the potential anti-atherosclerosis characteristics." (PMID 35310033, 2022). "In atherosclerosis model (LPS-stimulated Bovine aortic endothelial cells/plasmid transfected endothelial cells/HUVECS/VSMC), SFN reduced the expression of intracellular adhesion molecule (ICAM-1), VCAM-1 (vascular cell adhesion molecule-1), E-selectin, and MCP-1 (monocyte chemotactic protein-1)." (PMID 35163897, 2022). "In the early step of atherosclerosis, activated ECs release chemokines (eg. monocyte chemotactic protein 1, MCP-1) and adhesion molecules (eg., intercellular adhesion molecule 1, ICAM1 and vascular cell adhesion molecule 1, VCAM1), inducing the attachment of monocytes to the arterial vessel wall." (PMID 36160452, 2022). "The effects of sinomenine on VCAM-1 and pro-inflammatory factors including TNF-α, IL-1, and ET-1 suggest its potent repression on inflammatory and immune responses which facilitate the formation of foam cells and exacerbate the progression of plaque in atherosclerosis." (PMID 34660748, 2021).
atherosclerosis (continued). "Atherosclerosis starts with EC activation mainly due to lipid mediators such as oxidized low density lipoprotein (ox-LDL), which upregulates the expression of endothelial adhesion receptors such as intercellular adhesion molecule-1 (ICAM-1) and vascular adhesion molecule-1 (VCAM-1)." (PMID 33804952, 2021). "In addition to ICAM-1 and VCAM-1, CXC chemokine ligands (CXCL) have also been identified as key adhesion molecules in adhesion, migration, and recruitment of monocytes during the pathogenesis of atherosclerosis." (PMID 34388961, 2021). "In addition, HDL inhibits endothelial cell adhesion molecules, including vascular cell adhesion molecule 1 (VCAM-1), intercellular adhesion molecule-1 (ICAM-1) and E-selectin, which are responsible for the binding of monocytes at sites of developing atherosclerosis." (PMID 34064071, 2021). "Another way to target VCAM-1 is to exploit peptides that are characterized by high affinity and specificity for VCAM-1 binding: several research groups developed VCAM-1 targeting systems for the diagnosis and therapy of atherosclerosis and cancer, by exploiting VCAM-1 targeting peptides." (PMID 34371717, 2021). "This study revealed that MBcAbVCAM-1-5 detected VCAM-1 expression in early and established atherosclerotic lesions in vivo and ex vivo, but it is not yet ready for clinical translation because the atherosclerosis developed in the mouse model studied is not similar to human atherosclerosis." (PMID 33138124, 2020). "OA also can down-regulate the inflammation-related proteins VCAM-1 and MCP-1, LOX-1, therefore, we speculate that OA plays a role in the prevention and treatment of atherosclerosis by enhancing the flux of autophagic cells and reducing the inflammatory response." (PMID 32487223, 2020). "Besides, an olive extract rich in secoiridoids has shown its capacity to weaken initial steps of atherosclerosis due to significant reduction of endothelial dysfunction biomarkers such as E-selectin, VCAM-1, MCP-1, ICAM-1 and F4/80 in ApoE−/− mice, an atherosclerosis-prone mouse model." (PMID 33322700, 2020). "At 4 weeks after commencement of treatment, SAA increased aortic vascular cell adhesion molecule (VCAM)-1 expression and F2-isoprostane level and decreased cyclic guanosine monophosphate (cGMP), consistent with SAA stimulating endothelial dysfunction and promoting atherosclerosis." (PMID 32075280, 2020). "In another way, PCA has been shown to inhibit ICAM1 and vascular cell adhesion molecule 1 (VCAM-1)-dependent monocyte adhesion to activated HUVEC endothelium, as well as CCL2-mediated monocyte transmigration, thereby reducing the development of atherosclerosis in ApoE−/− mice." (PMID 32013236, 2020). "Therefore, decreased expression of VCAM-1 and MCP-1 suppresses the development of atherosclerosis." (PMID 30858489, 2019). "Various antibody-based or peptide-based theranostic nanocarriers targeting VCAM-1, ICAM-1, E- and P-selectin, or platelet endothelial cell adhesion molecule (PECAM-1) are described in the literature to deliver their cargo to endothelial cells in in vitro and in vivo models of atherosclerosis." (PMID 31382634, 2019). "In the development of atherosclerosis, adhesion proteins induce the recruitment of monocytes, so we evaluated the effect of nicotine and GTPCH1 on the expression of adhesion proteins such as intracellular adhesion molecule 1 (ICAM1) and vascular cell adhesion molecule 1 (VCAM1)." (PMID 30091833, 2018). "VCAM1 but not ICAM1 has been implicated in the early pathogenesis of atherosclerotic plaques, via promotion of monocyte adhesion and accumulation on vessel walls susceptible to developing atherosclerosis." (PMID 30563576, 2018). "Therefore, adhesion molecule expression ICAM-1 and VCAM-1 was not upregulated in the early progression of atherosclerosis and they are less likely to contribute to cardiomyopathy because of dyslipidemia." (PMID 30505360, 2018).
atherosclerosis (continued). "Other studies performed in early stages of atherosclerosis demonstrate that IL-17/IL-17RA axis has a pro-atherogenic role by promoting early monocyte recruitment into plaque through CCL5 production, endothelial VCAM-1 expression and increasing CXCL1 expression on the vessel lumen." (PMID 29375564, 2017). "Atherosclerosis in HAD rats was characterized by marked increases in aortic monocyte chemotactic factor-1 (MCP-1), intercellular adhesion molecule-1 (ICAM-1), and vascular cell adhesion molecule-1 (VCAM-1) mRNA compared with the ND group, according to real-time PCR." (PMID 26783398, 2016). "Circulating endothelial activation molecules (vascular cell adhesion molecule-1 (VCAM-1), intercellular adhesion molecule-1 (ICAM-1), E-selectin, and P-selectin), and carotid intima-media thickness (cIMT), were measured as parameters of vascular endothelial dysfunction and early atherosclerosis." (PMID 27941821, 2016). "Previous studies have illustrated that CAV-1 may be involved at the earlies stages of atherosclerosis development through increased LDL particle transcytosis, endothelial cells activation, and induced protherogenic molecule CD36 and vascular cell adhesion molecule-1 expression." (PMID 27124120, 2016). "Hence, we speculated that cilostazol inhibits the signaling of NF-kB and decreases transcription of different proteins, including ICAM-1, VCAM-1, E-selectin, TNF-α, interleukin-6 (IL-6), AGE, and ligands for RAGE in human atherosclerosis." (PMID 25666934, 2015). "VCAM-1 accelerates the migration of adherent leukocytes along the endothelial surface, and promotes the proliferation of smooth muscle cells; therefore, it is speculated that VCAM-1 may be involved in the pathogenesis of atherosclerosis." (PMID 26622332, 2015). "The authors also used a mouse model of atherosclerosis in the same study, the highly resolved PET images for each model allowed normal tissue to be clearly distinguished from atherosclerotic lesions, the infarct and the heterotopic allograft, in which VCAM-1 expression was increased." (PMID 25741532, 2015). "Atherosclerosis, precursor to cardiovascular diseases, is recognised as a chronic inflammatory disease of large arteries, involving cytokines, such as IFN-γ and TNF-α, adhesion molecules, such as ICAM-1 and VCAM-1, and several plasma inflammatory markers, such as hsCRP, IL-6, and fibrinogen." (PMID 26346892, 2015). "In contrast, salusin-α could selectively down-regulate the levels of IL-6 and TNF-α in plasma not MCP-1 and VCAM-1 in the aorta, suggesting little effects of salusin-α on inflammation in atherosclerosis progression." (PMID 24621517, 2014). "IL-6 also induces ICAM-1 expression on endothelial cells and may play a role in development and progression of atherosclerosis; adhesion molecules such as ICAM-1 and VCAM-1 play a significant role in cell recruitment within the intima during atheroma formation." (PMID 25490200, 2014). "AngII exerts effects on endothelial cells in vitro that may potentially promote atherosclerosis, including increased expression of VCAM-1; however, this has not been consistently observed." (PMID 23236507, 2012). "However, in RA and SLE patients without renal or vascular disease, serum concentrations of VCAM-1 are similar to the control population and the relationship to atherosclerosis is uncertain." (PMID 22962622, 2012). "However, the role of exercise on PCSK9, LOX-1 and VCAM-1 in atherosclerosis has not been reported." (PMID 32325897, 2020). "Furthermore, the expression of VCAM-1 and MCP-1 in the aorta was reduced by exercise training, suggesting that endurance exercise training might decrease aortic VCAM-1 and MCP-1 expression in preventing atherosclerosis." (PMID 30858489, 2019).
atherosclerosis (continued). "Inhibition of ER stress with 4-PBA greatly suppressed the increased VCAM-1 expression induced by pro-atherogenic TGRL, but only moderately lowered TGRL’s anti-atherogenic activity, suggesting that therapeutics targeting ER stress may provide efficacious treatment of atherosclerosis." (PMID 24205197, 2013). "In addition, the serum TNF-α and IL-1β levels were increased in atherosclerosis rabbits, and kaempferol groups showed lower TNF-α and IL-1β levels, indicating that the down-regulation of E-sel, ICAM-1, VCAM-1 and MCP-1 might be mediated by the reducing of TNF-α and IL-1β." (PMID 23895132, 2013). "In SLE, aspirin did not alter the level of several atherosclerosis biomarkers (homocysteine, high-sensitivity CRP, soluble VCAM-1, P-selectin, and thrombomodulin)." (PMID 29435447, 2017). "Although expression of both VCAM-1 and ICAM-1 is up-regulated in atherosclerotic lesions, VCAM1, but not ICAM1, plays a dominant role in the initiation of atherosclerosis." (PMID 25189624, 2014). "Transgenic mice lacking MCP-1, ICAM-1, or the fourth Ig domain of VCAM-1 (VCAM-1 expression is necessary for chorioallantoic fusion, rendering VCAM-1 knockouts lethal) severely limits atherosclerosis." (PMID 22489274, 2012). "In 2001, Myron I. Cybulsky demonstrated that VCAM-1, but not ICAM-1, plays a dominant role in the initiation of atherosclerosis." (PMID 22900050, 2012). "Although the HIV-infected rats did not display overt atherosclerosis, the up-regulation of LOX-1 and VCAM-1 indicates early atherogenesis in these rats." (PMID 19997643, 2009). "Additionally, resistin elevated the production of VCAM-1 and inflammatory cytokines, but not MCP-1, in the carotid arteries of the atherosclerosis model rabbit." (PMID 39558976, 2024).
endothelial dysfunction (524 papers, 2005 to 2026). In vascular diseases, endothelial dysfunction is a systemic pathological state of the endothelium (the inner lining of blood vessels) and can be broadly defined as an imbalance between vasodilating and vasoconstricting substances produced by (or acting on) the endothelium. "The pleiotropic effects of VCAM-1 in endothelial signalling mean that VCAM-1 activation is an essential step in several molecular mechanisms underlying endothelial dysfunction and, therefore, in a wide range of disease processes involving the vasculature." (PMID 40095109, 2025). "Elevated levels of soluble P-selectin and vascular cell adhesion molecule-1 (VCAM-1) indicative of endothelial dysfunction, were linked to DCI and poor 90-day mRS outcomes (p < 0.01)." (PMID 41173049, 2025). "Selected biomarkers were chosen based on prior evidence linking them to platelet activation (sCD40-L), systemic inflammation (hs-CRP), and endothelial dysfunction (VCAM-1) – all of which are implicated in CMVO pathogenesis." (PMID 40988197, 2025). "Elevated soluble vascular cell adhesion molecule-1 (sVCAM-1) and soluble intercellular adhesion molecule-1 (sICAM-1) levels implicated in the regulation of inflammation indicate endothelial dysfunction." (PMID 38558679, 2024). "Although it is associated with endothelial dysfunction, protein level of Vcam1 is underexplored in the vasculature in SLE models." (PMID 39234308, 2024). "ICAM-1 and VCAM-1 contribute to vascular inflammation, and these markers have been widely utilized as indicators of endothelial dysfunction, demonstrating a significant association with cardiovascular disease (CVD) risk and mortality in the general population." (PMID 39669584, 2024). "ET-1, E-selectin, ICAM-1, and VCAM-1, expressed in various disease states associated with endothelial dysfunction, serve as reliable markers of inflammation and endothelial dysfunction, playing crucial roles in the pathophysiology of cardiovascular diseases." (PMID 38251031, 2024). "Progression of endothelial dysfunction is associated with the increase in the expressions of chemokines, cellular adhesion molecules, and cytokines, such as VCAM-1, and systemic inflammatory markers, such as TNF-α, among others." (PMID 38195507, 2024). "Endothelial dysfunction and ongoing cardiovascular inflammation are caused by immune cells penetrating the arterial wall as a result of activated VCAM1 on endothelial cells, which attracts leukocytes, monocytes, and neutrophils." (PMID 37841916, 2023). "In our study, we showed that only VCAM-1 as a biomarker of endothelial dysfunction manifested higher levels in patients with a higher CV risk." (PMID 38255155, 2023). "In the general population, elevated VCAM-1 has been consistently associated with endothelial dysfunction." (PMID 36821530, 2023). "NF‐κB activation is a critical regulator of CAMs including ICAM‐1 and VCAM‐1 which causes the adhesion of monocytes to endothelial cells during endothelial dysfunction." (PMID 37457144, 2023). "Taken together, these studies support the view that high serum ICAM-1 and VCAM-1, as biomarkers of endothelial dysfunction and vascular damage, are associated with ventricular de/repolarization." (PMID 36710676, 2023). "Cell infiltration into the vessel wall is caused by inflammatory stimulation during endothelial dysfunction, and VCAM-1 is crucial to this process." (PMID 36408439, 2022). "Recently, our results demonstrated that Ang II-caused VCAM-1 overexpression can promote the infiltration of macrophages in arteries, leading to endothelial dysfunction and hypertension." (PMID 36467095, 2022). "These two inflammatory factors increase monocyte chemo-attractant protein-1 (MCP-1) and vascular cell adhesion molecule 1 (VCAM-1), thereby promoting leukocyte-endothelial cell adhesion, causing endothelial dysfunction." (PMID 36035922, 2022).